LEP (leptin)
Diseases named in the same sentence as LEP in open-access papers (continued):
Sharing a sentence is not in itself a finding about the gene and the disease.
Obesity (continued). "Obesity is a chronic subinflammatory state associated with an altered adipokine profile, with high levels of leptin and reduced adiponectin expression." (PMID 36980434, 2023). "Regrettably, the lack of detailed data of obesity and BMI made it unfeasible to study the influence of obesity/BMI on the association between leptin status and asthma." (PMID 36914629, 2023). "Leptin-deficient (ob/ob) mice, which develop obesity, hepatic steatosis, and diabetes as a result of hyperphagia and insulin resistance, also have a 10-fold higher rate of hepatic DNL compared with control mice." (PMID 37681411, 2023). "Although leptin can normally cross the BBB, its transport is impaired in obesity, causing leptin resistance." (PMID 37371113, 2023). "Monogenic obesity due to single-gene pathogenic variants in the leptin–melanocortin pathway, an essential energy homeostasis pathway, accounts for 6% of the total cases of severe early-onset obesity." (PMID 38003551, 2023). "Leptin was initially identified as a satiety hormone with low leptin levels or leptin deficiency causing obesity." (PMID 37189804, 2023). "An imbalance between the pro-inflammatory leptin and the anti-inflammatory adiponectin has been shown to be associated with an elevated risk of developing obesity-related complications." (PMID 37049592, 2023). "It is common for individuals with obesity since childhood to display signs of metabolic alterations, such as insulin resistance, elevated levels of leptin, and vitamin D deficiency." (PMID 37629427, 2023). "The increase in leptin levels caused by overfeeding provides a physiological signal that causes leptin resistance in obesity, as well as in other central and peripheral pathologies." (PMID 36674935, 2023). "Recent research found that personalized recombinant leptin therapy helped correct severe, early-onset obesity linked with leptin genetic variations in two kids." (PMID 37712012, 2023). "Clinically, the initial descriptions of young patients with obesity consequent to LEP or LEPR deficiency were rather similar." (PMID 37659411, 2023). "Then abnormal production and secretion of adipokines (including leptin, adiponectin, resistin, etc.)are also thought to play an important role in the association between obesity and systemic inflammation." (PMID 36790552, 2023). "The hypothalamus in particular is thought to be the primary leptin target that causes leptin's anti-obesity activity in the CNS." (PMID 37789370, 2023). "In mice with obesity-associated diabetes, leptin downregulation leads to overexpression of RAGE in β-cells and therefore inhibits insulin infusion and mediates AGE-elicited pancreatic islet apoptosis." (PMID 37446161, 2023). "Obesity is associated with characteristic physiological changes, including imbalances of energy regulation hormones, adipokines such as leptin and adiponectin and increased levels of estrone." (PMID 37628676, 2023). "Recent studies have shown that SH2B1, a gene implicated in leptin and insulin signaling, is a substantial contributor to the genetic architecture of obesity." (PMID 38434247, 2023). "We suggest that obesity-related elevation of leptin/obR signaling has pathogenic effects by increasing M1 macrophage polarization in obesity-related neutrophilic airway inflammation, and we provide a promising drug target for obesity-related asthma." (PMID 37488474, 2023). "Since maternal overweight and obesity are well-known risk factors for autism in children, a few longitudinal studies addressing leptin levels in the perinatal period and early childhood in the context of ASD have been conducted." (PMID 36902307, 2023). "To understand how obesity leads to leptin resistance and how leptin resistance causes AD to progress, we shed light on two mechanisms: inflammation and signaling pathway." (PMID 37363537, 2023).
Obesity (continued). "Studies have identified leptin, aromatase, insulin receptor, peroxisome-proliferator-activated receptor gamma (PPARγ), and lifestyle changes as other potential targets for obesity-associated breast cancer treatment." (PMID 37626871, 2023). "STAT3 phosphorylation deficiency in the hypothalamus results in central leptin-induced resistance and obesity." (PMID 37244925, 2023). "High leptin production caused by the dysfunction of or excess adipose tissue is often seen in obesity and cancer, notably in breast cancer." (PMID 37181043, 2023). "FVB/N ob/ob and C57BL/6J ob/ob mice are used to study obesity and its comorbidities as both murine lineages are leptin deficient thus maximizing hunger and the effects of the HFD." (PMID 37362441, 2023). "For example, hypomethylation of leptin is recognized as decreasing the risk of obesity through increasing leptin expression and restraining appetite." (PMID 36678251, 2023). "Chronic leptin deficiency in a genetic KO model (the Lepob/ob mouse) results in hyperphagia and obesity." (PMID 37222423, 2023). "Leptin, an adipokine secreted by adipocytes, is mainly associated with obesity, and the degree of leptin resistance in the blood plasma of most obese individuals is low." (PMID 36771320, 2023). "This indicated a possible causal link between raised leptin concentrations and impaired antiviral immunity in obesity, potentially through perturbed fatty acid metabolism." (PMID 37857661, 2023). "Leptin concentration tends to be higher in individuals with more adipose tissue, and obesity is associated with leptin resistance." (PMID 37834783, 2023). "The anti-obesity effect of Leptin was demonstrated in individuals bearing congenital leptin deficiencies." (PMID 37650871, 2023). "Mutations in the leptin gene leading to leptin deficiency are some of the causes of monogenic obesity with such symptoms as impaired satiety, hyperphagia, early onset of obesity, and many metabolic and immunological disorders." (PMID 36983642, 2023). "The transgenic mouse model of leptin deficiency induced obesity (ob/ob mice) leads to a continuous sensation of hunger, which causes the animals to continually search for food." (PMID 37034162, 2023). "This is explained by the fact that poor diet is associated with the prevalence of overweight and obesity, and obese women have higher serum leptin levels than obese men." (PMID 37686809, 2023). "Obesity, which is caused by long-term high-calorie consumption, can increase anxiety through insulin or leptin resistance, systemic inflammation, and hormonal dysregulation." (PMID 37926812, 2023). "In 1961, Lois Zucker developed this rat strain by mutating leptin, which leads to obesity from the third week of life." (PMID 37650104, 2023). "Abnormal leptin, adiponectin, and insulin levels are associated with obesity, diabetes, and other metabolic disorders." (PMID 36829148, 2023). "Leptin has also been associated with a higher reward response in the insula in participants with obesity compared to lean participants." (PMID 37012575, 2023). "We found that loss of leptin signaling to T cells was insufficient to influence glucose tolerance in obesity, although leptin deficiency did prevent impaired fasting glucose levels compared to control mice in the HFD setting, in a sex dependent manner." (PMID 37276236, 2023). "Among the various pro-inflammatory molecules associated with obesity and MS, leptin is particularly important, which is also a marker of long-term energy stores." (PMID 36788619, 2023). "Secondly, since obesity causes a low-grade inflammatory state, a higher production of IL-6, adiponectin, leptin, or TNF-α is present." (PMID 38068717, 2023). "Both higher circulating leptin levels and lower circulating adiponectin levels reflect obesity-associated alterations in the adipose tissue adipokinome." (PMID 37571390, 2023).
Obesity (continued). "Depression is notorious for being a risk factor for metabolic dysfunction associated with obesity, including an inflammatory response, high blood pressure, impaired insulin sensitivity, and impaired leptin sensitivity." (PMID 37373992, 2023). "The high content of phytol found in C. olitorius reduces leptin, which is associated with the reversal of insulin resistance in obesity." (PMID 37090773, 2023). "Among the adipokines secreted by adipose tissue, leptin was consistently associated with the development of obesity-related complications." (PMID 37242271, 2023). "Meanwhile, obesity has been found to be associated with altered collagen structure and resistance to leptin, leading to impaired wound healing." (PMID 36997989, 2023). "Firstly, how obesity is linked to dementia, secondly, how adiponectin and leptin dysregulation is developing cognitive decline." (PMID 37363537, 2023). "Sleep deprivation is associated with incident obesity, perhaps mediated by dysregulation in leptin and ghrelin — hormones important in regulation of appetite." (PMID 37148488, 2023). "Weight loss treatment with VLED in patients with PsA and obesity was accompanied by significant reductions in serum IL-23 and leptin and significant increases in serum tot-adiponectin and HMW adiponectin." (PMID 37501212, 2023). "In turn, decreased blood Ob-Re levels are associated with leptin resistance linked to obesity and diabetes." (PMID 38068822, 2023). "More recently, our group reported that leptin concentrations influence the association of obesity with parameters related to insulin resistance, such as non-esterified NEFA levels." (PMID 37242271, 2023). "Leptin, an adipokine and neuroendocrine hormone closely linked to obesity, regulates not only adipogenesis and energy balance but also functioning of the thymus." (PMID 37888466, 2023). "According to this, the improvement of leptin levels is associated with an improvement in the state of health of people with obesity since leptin increases the oxidation of glucose, normalizing the rate of glycogen synthesis." (PMID 37238961, 2023). "Leptin is associated with obesity, therefore several effort has been dedicated to the role of leptin in CRC development." (PMID 37942199, 2023). "Leptin is a 16 kDa pleiotropic peptide hormone encoded by the obesity (Ob) gene that acts by binding to the Ob receptor (ObR) to regulate appetite and energy expenditure." (PMID 37893085, 2023). "Leptin was initially cloned in 1994, and this groundbreaking discovery has had a profound impact on our understanding of the mechanisms that underlie obesity and metabolic disorders." (PMID 38027481, 2023). "The pro-inflammatory state in obesity is associated with changes in adipokine release by adipose tissues, such as leptin and adiponectin." (PMID 38004453, 2023). "Non-T2 endotypes with mixed Th17/ILC3 (type 3 immune response) and Th1/ILC1 (type 1 immune response) profiles, both of which are generated by leptin, are the principal drivers of obesity-linked asthma in adulthood." (PMID 37789370, 2023). "A high-salt diet also activates the aldose reductase-fructokinase pathway in the liver and hypothalamus, which leads to endogenous fructose production with the development of leptin resistance and hyperphagia that cause obesity, IR, and NAFLD." (PMID 36788518, 2023). "Suggesting a potential interaction, in leptin-deficient (ob/ob) and diet-induced obesity models of obesity, there is evidence of increased circulating monocytes, particularly the inflammatory monocyte subsets and lung tissue monocytes." (PMID 37759429, 2023). "To elucidate the effects of obesity on the lipid composition of EVs-AT, we performed a comparative lipidomic analysis between the obese and lean state on the leptin-deficient (ob/ob) mouse." (PMID 38028559, 2023). "Congenital leptin deficiency leads to severe dysregulation of satiety and food intake resulting in obesity." (PMID 36833305, 2023).
Obesity (continued). "Circulating leptin levels in the blood are associated with the extent of obesity; thus, leptin is a sensitive biomarker to indicate obesity." (PMID 37297447, 2023). "Monogenic forms of obesity due to deficiencies in leptin and leptin receptor genes are characterized by early-onset of rapid weight gain, hyperphagia and insulin resistance, frequent infection, and pituitary hormone deficiency." (PMID 37329217, 2023). "Since mechanistic studies of liver fibrogenesis are difficult to conduct in patients, current knowledge of obesity-induced liver fibrosis is mainly derived from Leptin-deficient animal models." (PMID 37705071, 2023). "Another polymorphism, C478T, within the PPARγ gene, has been associated with higher leptin levels in individuals living with obesity, and it has been linked to obesity and an increased fat mass in women." (PMID 37571382, 2023). "Surprisingly, it has been shown that there are large levels of circulating leptin in the blood of people with obesity, which has been associated with the development of resistance to this hormone in people with excessive body mass." (PMID 36978817, 2023). "The CB1R system, linked to metabolic syndrome, including leptin and insulin resistance, is triggered by both central and peripheral stimulations during obesity." (PMID 38068822, 2023). "In the field of obesity, it led to the cloning of leptin, the first gene whose absence causes obesity and was shortly identified in human families." (PMID 37242136, 2023). "In humans, extreme hyperphagia and obesity were caused by leptin-gene mutations and leptin-receptor abnormalities." (PMID 37238961, 2023). "Nonetheless, it has been reported that even in individuals with obesity, 1 wk of moderate altitude exposure increases leptin levels and induces weight loss supporting transferability." (PMID 36476162, 2023). "The most direct evidence for a role of leptin in establishing the low-grade systemic inflammatory response associated with obesity is that WAT inflammation was strongly reduced when LepR were knocked out in mouse leukocytes." (PMID 36769012, 2023). "Obesity is caused by a leptin deficit or genetic flaws in the leptin signaling pathway's constituent parts." (PMID 37789370, 2023). "Leptin, a 167-amino-acid protein primarily produced by adipocytes, is encoded by the obesity gene and has a molecular weight of approximately 16 kDa." (PMID 37593311, 2023). "In a diet-induced obese mouse model, leptin mediates atrial fibrosis and AF and a higher level of serum leptin is associated with obesity." (PMID 37623336, 2023). "The main risk factor for the development of overweight and obesity is thought to be leptin resistance." (PMID 37789370, 2023). "Another FTO variant rs8061518 in Intron 3 was associated with decreased risk of obesity and low concentration of leptin." (PMID 37612540, 2023). "The cause of obesity and metabolic syndrome can be attributed to the methylation process affecting known as insulin-like growth factor 2 (IGF2) gene and the hypermethylation of two obesity-associated genes, leptin and tumor necrosis factor (TNF)." (PMID 38248733, 2023). "In this early‐life model, greater caries experience in childhood was associated with obesity and higher leptin levels by age 45 years." (PMID 37920118, 2023). "Leptin therapy has shown promise in treating and alleviating ectopic fat accumulation associated with obesity." (PMID 38138996, 2023). "Leptin is an anorexigenic hormone that is secreted by white adipose tissue, and despite the anorectic effect of plasma leptin, it is correlated with body fat content, suggesting that obesity is associated with a state of leptin resistance." (PMID 37442561, 2023). "Specifically, obesity is associated with increased levels of leptin, free fatty acids, and pro-inflammatory cytokines." (PMID 37880430, 2023).
Obesity (continued). "The direct impact of obesity on fertility is associated with elevated levels of leptin, triglycerides, and free fatty acids in ovarian follicular fluid, as well as the presence of oxidative stress and inflammatory mediators." (PMID 37371662, 2023). "Genetic disruptions involving the hypothalamic leptin–melanocortin signaling pathway account for the vast bulk of genetic predispositions to obesity." (PMID 37835041, 2023). "Poor sleep quality and increased stress influences leptin and ghrelin levels in the body which increase appetite and reduce energy expenditure, this eventually results in obesity and increased risk of hypertension." (PMID 36895825, 2023). "It seems the underlying mechanism in the association between obesity and elevated risk of MS refers to a significant increase in leptin level as an adipose tissue hormone that has a role in adaptive and innate immunity." (PMID 37122312, 2023). "First, the predicted leptin activation of the melanocortin action on body weight reduction contradicts notions of obesity development associated with hyperleptinemia." (PMID 37069175, 2023). "It has recently been proposed that leptin is a mechanistic link between reduced sleep duration and higher obesity risk among children." (PMID 37322451, 2023). "Endocrine biomarkers associated with maternal obesity included leptin, insulin, thyroid stimulating hormone, adiponectin, progesterone, free T4 and human chorionic gonadotropin." (PMID 36520252, 2023). "HFD and the consequent hypothalamic inflammation ultimately lead to some degree of leptin resistance, a hallmark of obesity." (PMID 36832370, 2023). "The development of a monogenic type of obesity is caused by the presence of a pathogenic variant in the DNA sequence in one of the genes of the leptin-melanocortin system (LEP, LEPR, POMC, PCSK1, and MC4R)." (PMID 37888112, 2023). "Leptin is a hormone secreted predominantly from adipocytes, has anorectic action, and its deficiency induces obesity and insulin resistance." (PMID 38203600, 2023). "Leptin, a key adipose-derived hormone that regulates eating behavior and body weight, is associated not only with obesity but also with depression." (PMID 37387537, 2023). "Mutations in the genes encoding the MC4R, leptin, and leptin receptor are commonly reported in various populations to cause monogenic obesity." (PMID 37329217, 2023). "It is known that aging, a high-fat diet, and adipose tissue dysfunction caused by obesity increase the leptin/adiponectin ratio, which is associated with lung function and fibrosis markers." (PMID 38001499, 2023). "The high plasma leptin level was an independent risk predictor for significant weight gain (adjusted odds ratio (aOR) = 2.29, and p = 0.030) and new-onset obesity (aOR = 6.64, and p = 0.016)." (PMID 37509115, 2023). "Leptin is unable to exert its effect during diet-induced obesity, and several molecular alterations have been associated with attenuated leptin signalling, inducing the metabolic syndrome parameters reduced by a PBJ diet." (PMID 37049725, 2023). "These drugs have been used to treat patients with monogenic obesity caused by pathogenic variants in the leptin–melanocortin pathway." (PMID 37329217, 2023). "In general, these results suggest a novel, rather protective role of the leptin-lowering allele in individuals with obesity." (PMID 36833305, 2023). "The main adipokines associated with development of obesity are leptin, adiponectin, resistin, TNF-alpha, and IL-6." (PMID 37629396, 2023). "In this study, Slc7a5 deficiency led to leptin insensitivity in LepR-expressing neurons and decreased sympathetic outflow prior to the onset of obesity." (PMID 36862514, 2023). "C57BL/6 mice were used as experimental animals, and they are often used as obesity-prevention models because they lack the leptin gene and cannot control appetite, causing obesity." (PMID 37432154, 2023).